POU5F1 (POU class 5 homeobox 1)
Description:
Transcription factor that binds to the octamer motif (5'-ATTTGCAT-3'). Forms a trimeric complex with SOX2 or SOX15 on DNA and controls the expression of a number of genes involved in embryonic development such as YES1, FGF4, UTF1 and ZFP206. Critical for early embryogenesis and for embryonic stem cell pluripotency.
Synonyms: Oct-3; Oct-4; OTF-3; OCT3; OCT4; OTF3; MGC22487; Oct3/4; OCT4Borf1; OTF4
Tractability: Small molecule: a structure with a bound ligand is known. PROTAC: UniProt records ubiquitination sites on it; ubiquitination databases record sites on it.
Target class: Transcription factor
Safety:
Unwanted effects reported when the protein is acted on. In parentheses: how it was acted on, where the effect was seen, and who reports it.
severe cutaneous adverse reactions (source: ClinPGx)
Gene: Protein-coding gene on chromosome 6 (31,164,337 to 31,180,731, reverse strand). Ensembl gene ENSG00000204531.
Subcellular location: Cytoplasm; Nucleus
Subcellular location (Human Protein Atlas): Nucleoplasm; Cytosol; Mitochondria
Pathways (Reactome):
Developmental Biology: Formation of the anterior neural plate; Germ layer formation at gastrulation; POU5F1 (OCT4), SOX2, NANOG activate genes related to proliferation; POU5F1 (OCT4), SOX2, NANOG repress genes related to differentiation; Specification of the neural plate border; Transcriptional regulation of pluripotent stem cells
Reproduction: Specification of primordial germ cells
Gene Ontology:
Molecular function: DNA binding; DNA-binding transcription factor activity; DNA-binding transcription repressor activity, RNA polymerase II-specific; miRNA binding; protein binding; RNA binding; sequence-specific DNA binding; sequence-specific double-stranded DNA binding; transcription cis-regulatory region binding; ubiquitin protein ligase binding; DNA-binding transcription factor activity, RNA polymerase II-specific; RNA polymerase II cis-regulatory region sequence-specific DNA binding
Biological process: endodermal cell fate specification; negative regulation of miRNA transcription; negative regulation of transcription by RNA polymerase II; positive regulation of transcription by RNA polymerase II; regulation of DNA-templated transcription; regulation of gene expression; response to wounding; somatic stem cell population maintenance; anatomical structure morphogenesis; blastocyst development; regulation of asymmetric cell division; regulation of transcription by RNA polymerase II
Cellular component: cytoplasm; cytosol; nucleoplasm; nucleus; RNA polymerase II transcription regulator complex
Genetic constraint (gnomAD): Loss-of-function variants: 6 observed, 37.08 expected, observed/expected ratio (o/e) 0.16, 90% interval 0.088 to 0.32. The synonymous counts are far from expectation, so gnomAD's model fits this gene poorly and the ratio says little. Missense variants: 286 observed, 439.04 expected, observed/expected ratio (o/e) 0.65, 90% interval 0.59 to 0.72. Synonymous variants: 147 observed, 188 expected, observed/expected ratio (o/e) 0.78, 90% interval 0.68 to 0.9.
Cancer hallmarks: proliferative signalling (promotes); invasion and metastasis (promotes); cell replicative immortality (promotes)
Homologues: Orthologues: chimpanzee POU5F1 (100% identical), rabbit POU5F1 (90% identical), guinea pig Pou5f1 (85% identical), rat Pou5f1 (84% identical), mouse Pou5f1 (84% identical), dog POU5F1 (73% identical), zebrafish pou5f3 (42% identical), Drosophila melanogaster vvl (37% identical), zebrafish pou3f1 (34% identical), tropical clawed frog pou3f1 (32% identical), Caenorhabditis elegans ceh-18 (29% identical), Drosophila melanogaster acj6 (25% identical), and 1 more. Paralogues in human: POU5F1B (96% identical), POU5F2 (41% identical), POU3F3 (37% identical), POU2F1 (36% identical), POU3F4 (35% identical), POU3F1 (35% identical), POU3F2 (34% identical), POU2F2 (32% identical), POU2F3 (30% identical), POU1F1 (26% identical), POU4F3 (26% identical), POU4F1 (25% identical), and 5 more.
Diseases named in the same sentence as POU5F1 in open-access papers:
POU5F1 is named in the same sentence as 370 diseases in open-access papers, as found by Europe PMC text mining. Sharing a sentence is not in itself a finding about the gene and the disease. The quoted sentences say what the papers report.
breast carcinoma (339 papers, 2008 to 2026). "Interrogation of KEGG disease and DiSgeNET databases revealed an association between APC2 gene and colorectal cancer, medulloblastoma and breast cancer, while POU5F1 was mainly associated with germ cell tumors." (PMID 33503040, 2021). "rs1108842 in gene GNL3, rs3785181 in gene GAS11, rs879882 in gene POU5F1 and rs2523608 in gene HLA-B are reported to have a high probable association with tumor or breast cancer." (PMID 30072632, 2018). "In breast cancer, POU5F1 is associated with the ERα's tumor suppressor function." (PMID 34457116, 2021). "Interestingly, our approach revealed a group of novel genes that can differentiate basal-like breast cancer from other breast cancer subtypes, including the POU5F1 gene (OCT4), which was previously found to be associated with TNBC and linked to cancer stem cells and worse patient outcome." (PMID 33304345, 2020). "In breast cancer, PD-L1 can promote cancer cell stemness by supporting the expression of the stem cell master transcription factors Oct-4 (POU5F1 gene) and Nanog64." (PMID 40240529, 2025). "Multiple breast cancer stem cell markers such as POU5F1, CD56, CD49f, and CD201/PROCR were also upregulated by C328-VIM, demonstrating increased stemness characteristics in MCF-7 cells as judged by the RNA-Seq analysis." (PMID 40690373, 2025). "A previous study identified POU5F1 as a potential candidate for predicting metastasis in human breast cancer." (PMID 38951817, 2024). "Breast cancer with lymph node metastases were in general associated with lower levels of the CSC genes ALDH1A3 and CD44, pluripotency markers POU5F1 and NEAT1, EMT marker SLUG, and drug resistance associated gene ERBB2, after DOX treatment." (PMID 38124067, 2023). "For example, poor survival is associated with high expression of OCT4 (protein encoded by POU5F1 gene) in gastric cancer, high expression of NANOG in lung and breast cancer, or high expression of SOX2 in gastric cancer." (PMID 32664372, 2020). "POU5F1/Oct-4 expression levels in breast cancer tissues were significantly higher in both the SLN metastasis and non-SLN metastasis groups (P = 0.003 and P = 0.030, respectively)." (PMID 26931354, 2016). "Taking the example of POU5F1 gene, previous studies showed that the expression of this gene is required for the maintenance of transformed breast cancer cells and suggested its utility as a novel clinical biomarker and a potential target for gene-specific therapy of breast cancer." (PMID 33503040, 2021). "Elevated expression of POU5F1 predicted poor prognosis of OS in bladder cancer, breast cancer, colorectal cancer, esophageal cancer, gastric cancer, LIHC, head and neck cancer, lung cancer and other cancers, including ovarian cancer, cervical cancer, neuroblastomas, and pancreatic cancer." (PMID 32978904, 2020). "In Du145 cells, the overexpression of HAPTOV1 also associated to significantly increased levels of stemness genes LIN28A, ALDH1A1 and MYC, whereas in PC3 cells it associated to a significant expression of LIN28A, MYC, NANOG and POU5F1 genes, in agreement with reports in breast cancer cells." (PMID 28938627, 2017). "The upregulated differentially expressed breast cancer stem cell markers included CD56/NCAM1, POU5F1, PROCR/CD201, ITGA6, and the downregulated were ESR1, PGR, HER2/ERBB2, ABCG2, CD44, CD24, EPCAM, and CDH1." (PMID 40690373, 2025). "Gene expression correlation analysis revealed that USP30 negatively correlates with the expression of stem cell markers such as MMP2, MMP9, MYC, OCT4(POU5F1), NANOG, ALDH1A3, CD133 (PROM1), EPCAM, CD24, and ITGA6 in breast cancer cohorts." (PMID 41306556, 2025). "In the TCGA breast cancer dataset, SDC1 expression was notably correlated with the stem cell biomarkers CD133, CD44, CD24, POU5F1, SMAD2, and NANOG at the transcriptional level." (PMID 41364407, 2025).
breast carcinoma (continued). "Further, HMGCS1 can induce transcriptional upregulation of pluripotency genes POU5F1 (Oct4) and SOX2 and is a key mediator of cancer stem cell enrichment in breast cancer." (PMID 37958351, 2023). "Expression of the six BCPRS genes (IFNA13, HEY1, NKX2-3, NR2F1, POU5F1, and YY1) in breast cancer tissues was analyzed using Tabula Muris's FACS and droplet methods." (PMID 34457116, 2021). "The low expression level of POU5F1 and YY1 and high expression level of HEY1, IFNA13, NKX2-3, and NR2F1 were significantly related to poor prognosis in breast cancer." (PMID 34457116, 2021). "A multivariate Cox regression model was employed to establish a predictive model containing 6 characteristic genes (HEY1, IFNA13, NKX2-3, NR2F1, POU5F1, and YY1) correlated with the prognosis of breast cancer." (PMID 34457116, 2021). "β-catenin binds POU5F1/OCT4 in embryonic stem cells, it stimulates human NANOG promoter activity and it regulates SOX2 activity in breast cancer cells." (PMID 34199594, 2021). "In summary, BCPRS and BCPRS-related genes (HEY1, IFNA13, NKX2-3, NR2F1, POU5F1, and YY1) can be used to evaluate the immune microenvironment and tumor purity in breast cancer patients." (PMID 34457116, 2021). "Simultaneously, overexpression of POU5F1 was related to shorter DFS in head and neck cancer, breast cancer, LIHC, colorectal cancer, and other cancers, including lung cancer, gastric cancer, cervical cancer, and acute myeloid leukemia." (PMID 32978904, 2020). "The Hollern Squamous Breast Tumor gene set is positively correlated with POU5F1 and SOX2 gene expression and consists of genes that have high expression in mammary tumors of squamous epithelium histology." (PMID 32899474, 2020). "Notably, unique metastatic biomarkers found in mFMC, such as POU5F1 (OCT4) and LAMA1, have been identified in human breast cancer." (PMID 38951817, 2024). "Therefore, a neural network-based model was constructed to predict cell types in breast cancer tissues based on genes YY1, POU5F1, NKX2-3, NR2F1, HEY1, and IFNA13." (PMID 34457116, 2021). "Furthermore, neural network-based deep learning models were established to predict breast cancer cell types using BCPRS-related genes (HEY1, IFNA13, NKX2-3, NR2F1, POU5F1, and YY1)." (PMID 34457116, 2021). "POU5F1/Oct-4 expression levels in breast cancer tissues are significantly associated with SLN and non-SLN metastasis, indicating that POU5F1/Oct-4 is a potential candidate for predicting metastasis." (PMID 26931354, 2016). "This study is the first to determine that positive POU5F1/Oct-4 expression levels are associated with SLN metastases and non-SLN metastases in early-stage breast cancer patients." (PMID 26931354, 2016). "Further, CDC42 and POU5F1 gene expression level were relatively higher (>8 fold) when uPAR+/int β1+ compared with uPAR−/int β1− CTC subsets in breast cancer patient without BCBM." (PMID 26631983, 2015). "The POU class 5 homeobox 1 (POU5F1) gene, a transcription factor involved in the self-renewal of undifferentiated stem cells and induction of embryonic pluripotency via metabolic mechanisms, has been shown to be involved in β-cell dedifferentiation in type 2 diabetes and is altered in breast cancer." (PMID 37606455, 2023). "More studies that could demonstrate the newly discovered association between the expression of POU5F1/Oct-4 and non-SLN metastasis are needed, in order to explore other new predictors that might exempt breast cancer patients from undergoing complete axillary dissection." (PMID 26931354, 2016). "Moreover, multivariate analysis results revealed that POU5F1/Oct-4 was significantly associated with non-SLN metastases, which indicates that high POU5F1/Oct-4 expression levels may be an indicator of non-SLN metastasis in breast cancer patients." (PMID 26931354, 2016).
breast carcinoma (continued). "A total of 121 patients were retrospectively selected between May 2010 and March 2013 to investigate the relationship between POU5F1/Oct-4 expression in breast cancer tissues and non-sentinel lymph node (non-SLN) metastases and to validate the Memorial Sloan-Kettering Cancer Center (MSKCC) nomogram." (PMID 26931354, 2016). "In the present study, we investigated the relationship of the expression of POU5F1/Oct-4 between breast cancer tissues and non-SLN metastases to determine a substitute for complete axillary dissection during the treatment of breast cancer." (PMID 26931354, 2016). "More studies on POU5F1/Oct-4 are needed to further explore its potential of being a predictor for SLN and non-SLN metastasis in breast cancer tissue." (PMID 26931354, 2016).
lung carcinoma (169 papers, 2008 to 2025). "It has been reported that POU5F1 maintains the CSC-like properties of lung cancer cells and is associated with poor prognosis in lung adenocarcinoma." (PMID 38062041, 2023). "In the current study, we explored the association of 17 potentially functional SNPs in POU5F1 gene with the development of lung cancer in 1,341 cases and 1,982 healthy controls." (PMID 26824036, 2015). "Moreover, several stem cell factors are reported to be important CSC markers in lung cancer, such as octamer-binding transcription factor 4 (Oct4, encoded by the POU5F1 gene), Nanog homeobox (Nanog, encoded by the NANOG gene) and ABCG2." (PMID 37726816, 2023). "To test this hypothesis, we conducted a case-control study including 1,341 cases and 1,982 controls to investigate the association between functional polymorphisms in POU5F1 and lung cancer risk." (PMID 26824036, 2015). "To test this hypothesis, we conducted a case-control study to explore the association between 17 potentially functional SNPs in POU5F1 gene and the lung cancer risk in 1,341 incident lung cancer cases and 1,982 healthy controls in a Chinese population." (PMID 26824036, 2015). "We speculate that variant genotype of rs887468 might lead to alternative splicing events and disequilibrium for different isoforms of POU5F1, suggesting a biological plausible mechanism for lung cancer risk." (PMID 26824036, 2015). "In summary, our case-control study reported 2 potential functional SNPs in POU5F1 gene that may affect the risk for lung cancer in a Chinese population." (PMID 26824036, 2015). "We hypothesized that functional polymorphisms in POU5F1 may play an important role in modifying the lung cancer risk." (PMID 26824036, 2015). "However, the mechanisms of aberrant POU5F1 expression in lung cancer underlying invasion and metastasis remain elusive." (PMID 24386189, 2013). "One possible explanation for the association between rs887468 and lung cancer risk might be that the variant genotype alters interactions of the loci with transcription factors and results in aberration in function of POU5F1 gene and elicits procedure of carcinogenesis." (PMID 26824036, 2015). "Therefore, we postulated that potentially functional genetic variation within POU5F1 might modify the susceptibility to lung cancer." (PMID 26824036, 2015). "In HCT116 cells (colorectal cancer) and A549 cells (lung cancer), whose LVRN was knocked out by the CRISPR‐Cas9 system, POU5F1 expression was also shown to be associated with that of LVRN." (PMID 41024351, 2025). "In the context of lung cancer, cells exhibiting high levels of POU5F1 expression have been observed to display resistance towards conventional treatment methods, including cisplatin, etoposide, paclitaxel, and targeted therapy with gefitinib." (PMID 38062041, 2023). "Multiple cancer‐related KEGG pathways were enriched in the high POU5F1 phenotype, such as bladder cancer, colorectal cancer, non‐small cell lung cancer, and renal cell carcinoma." (PMID 32978904, 2020). "Taken together, POU5F1 expression is crucial for the self-renewal and oncogenic potentials of lung cancer stem cells." (PMID 26824036, 2015). "In the hypoxia conditions, POU5F1 can promote CD133 expression in the lung cancer cells, which is a specific cell surface marker for cancer stem cells." (PMID 26824036, 2015). "It was also suggested that silencing KPNA2 could decrease the nuclear translocation of POU class 5 homeobox 1 (Oct4), suppressing the proliferation of lung cancer cells." (PMID 27849024, 2016). "Our findings indicate that POU5F1 is required for controlling cell invasion and migration via direct regulation of MMP-2 in lung cancer, and support the idea that POU5F1 and MMP-2 will be useful as potential biomarkers of prognosis and novel targets for lung caner therapy." (PMID 24386189, 2013). "Our data indicate that both POU5F1 and MMP-2 may contribute to tumor initiation and invasion–metastasis phenotype of lung cancer." (PMID 24386189, 2013).
glioma (123 papers, 2009 to 2026). A benign or malignant brain and spinal cord tumor that arises from glial cells (astrocytes, oligodendrocytes, ependymal cells). "NANOG, SOX2 and POU5F1, three stemness-associated genes that are part of the FA-BSA-NP delivery system, could facilitate autophagy inhibition and chemotherapy efficacy in glioma therapy." (PMID 34475426, 2021). "Consistent with NS-culture-derived glioma cells with high invasiveness, genes highly expressed in 51A were those encoding markers of neural stem/precursor cells (NANOG, POU3F2, POU5F1, and SALL2), and pro-invasive proteins (AGAP2, EPHA2, FOXM1, PDGFRA, and TNC)." (PMID 29113349, 2017). "Similarly, SOX4 and POU class 5 homeobox 1 (OCT-4) proteins were also shown to activate SOX2 transcription in glioma initiating cells." (PMID 23613880, 2013). "The data showed that IPS reprogramming factors and pluripotency-related genes (POU5F1, SOX2, KLF4, MYC and NOTCH1) were detected in almost all histologic types and grades of gliomas." (PMID 36435765, 2022). "We and others have shown previously that sphere cultures expanded from glioma LN18 cells in serum-free medium with growth factors are characterized by the higher expression of pluripotency markers (NANOG, POU5F1, SOX2, CD133)." (PMID 30654849, 2019). "We have previously implemented a protocol to cultivate LN18 sphere cultures enriched in glioma CSCs which expressed higher levels of the pluripotency markers: NANOG, POU5F1, SOX2, and CD133 as compared to the parental/adherent tumor cells." (PMID 30654849, 2019). "Furthermore, ITE bound to AHR and inhibited the transcription of POU5F1 in glioma stem cells, which led to the inhibition of tumor growth in the U87MG xenograft glioma model." (PMID 40283908, 2025). "While the mRNA levels of genes related to pluripotency (SOX2, KLF4, MYC and NOTCH1) were not obviously correlated with the clinical glioma grade or outcome, the mRNA level of POU5F1, which also plays a crucial role in PGC specification, was often linked to a higher glioma grade and poor outcome." (PMID 36435765, 2022). "LN18 glioma cells grown as non-adherent cells at a low density under serum-free conditions form spheres and display higher expression of stemness markers (NANOG, POU5F1, SOX2 and PROM-1) than adherent LN18 cells." (PMID 33050631, 2020).